ULBP2 (UL16 binding protein 2)
Diseases named in the same sentence as ULBP2 in open-access papers (continued):
Sharing a sentence is not in itself a finding about the gene and the disease.
breast carcinoma (16 papers, 2014 to 2025). "This study aims to investigate how RES affects the expression of ULBP2 and the sensitivity of breast cancer (BC) cells to NK cell cytotoxicity, along with the underlying mechanisms." (PMID 39963142, 2025). "The data indicate that RES upregulates ULBP2 expression in breast cancer cells and concurrently suppresses tumor growth in an in vivo setting." (PMID 39963142, 2025). "Altogether, the data demonstrate that the JNK/c-Jun pathway contributes to the promotion of ULBP2 expression in breast cancer cells and, to a certain extent, is involved in the mechanism by which miR-17-5p modulates ULBP2." (PMID 39963142, 2025). "Among these pathways, three are particularly relevant to breast cancer and ULBP2 regulation: mammary gland, invasive breast cancer, and cellular responses to stress." (PMID 39963142, 2025). "Our earlier investigation has demonstrated that the downregulation of MICA/B and ULBP2 by some NKG2D ligand-targeting microRNAs (miRNAs) resulted in a diminished NK cell-mediated cytotoxic response against breast cancer cells." (PMID 39963142, 2025). "RES induces ULBP2 expression and consequently enhances breast cancer cell elimination by NK cells through the suppression of miR-17-5p and activation of the MINK1/JNK/c-Jun cascade." (PMID 39963142, 2025). "A high surface expression level of ULBP2 significantly facilitates the recognition and subsequent elimination of breast cancer cells by NK cells." (PMID 39963142, 2025). "Extracellular signal regulated kinase (ERK), a component of MAPK signaling cascade, was verified to promote ULBP2 expression in breast cancer in our previous research, which indicated the involvement of MAPK signaling in NKG2DL regulation." (PMID 39963142, 2025). "Herein, miR-17-5p was demonstrated to suppress ULBP2 expression in breast cancer line MDA-MB-231 and MCF7 cells." (PMID 39963142, 2025). "This further indicates that miR-17-5p influences the recognition and killing of breast cancer cells by NK cells through its effect on ULBP2 expression." (PMID 39963142, 2025). "Our findings revealed that the mean value of ULBP2 expression was significantly elevated in breast cancer specimens (n=1104) compared to a cohort of adjacent normal breast tissue samples (n=113)." (PMID 39963142, 2025). "Herein, RES was found to effectively upregulate the expression of ULBP2, a pivotal component of NKG2DLs, thereby augmenting the cytolytic activity of NK cells against breast cancer cells both in vitro and in vivo." (PMID 39963142, 2025). "LncRNA UCA1 was found to enhance the expression of ULBP2 and promote the detachment of soluble ULBP2 from the cell surface, making it resistant to NK cells-mediated killing in breast cancer." (PMID 38254782, 2024). "Members of the miR-17-92 cluster, miR-20a, miR-20b, miR-93, and miR-106b, downregulated the expression of MICA/B and ULBP2 in breast cancer cell lines, affecting the capacity of NK cells to recognize and eliminate the tumor cells." (PMID 32316552, 2020). "In particular, miRNAs belonging to the miR-17-92 cluster were downregulated by HDACi leading to the upregulation of MICA/B and ULBP2 and enhancing tumor cell lysis by NK in different hepatocarcinoma and breast cancer cell lines." (PMID 32316552, 2020). "This shows that the NKG2D ligands MICA and ULBP2 are crucial for NK cell cytotoxicity against these breast cancer cells." (PMID 28771222, 2017). "The importance of ligands expression for tumor cell recognition by NK cells is a key factor for anti-tumor immune response, as illustrated by the strong prognostic value of MICA/MICB, RAET1G, and ULBP2 expression in colorectal cancer and breast cancer." (PMID 24715892, 2014). "In breast cancer, MICA/B ligands and ULBP2 are associated with a longer relapse-free period." (PMID 40013140, 2025). "Moreover, IHC and western blot analyses confirmed RES promoted ULBP2 expression in xenograft tumors, consistent with the findings obtained from breast cancer cell lines in vitro." (PMID 39963142, 2025).
breast carcinoma (continued). "RES was demonstrated to augment ULBP2 expression in four breast cancer cell lines." (PMID 39963142, 2025). "However, in the setting of colorectal and breast cancers, high NKR ligand MICA/B and ULBP2 expression was associated with a better prognosis for patients." (PMID 36839682, 2023). "Similarly, our analysis revealed that ULBP2 is upregulated in breast cancer with detrimental effects on patient overall survival." (PMID 33216733, 2020). "In addition, a further research was made on the functions of high risk immune gene ULBP2 and low risk immune gene TRDV1 which regulated by RUNX3, the results showed that down-regulation of ULBP2 suppressed breast cancer cell proliferation and TRDV1 had the opposite functions." (PMID 36092942, 2022). "Besides, the prognostic value of ULBP2 was also found in ovarian cancer and breast cancer." (PMID 33909599, 2021). "However, the shedding of soluble ligands in the circulation strongly impairs NK cell functions and has been linked with tumorigenesis and tumor progression and high serum concentration of ULBP2 presents a strong prognostic value in breast cancer, colorectal cancer, and melanoma." (PMID 24715892, 2014). "A recent study showed that ULBP2 expression correlates with the immunosuppressive TME and immunotherapy in breast cancer." (PMID 40775202, 2025). "To evaluate the expression of NKG2DL in primary breast cancer material (n = 200), we used the TCGA database analysis and observed predominant expression of MICA, MICB and ULBP2." (PMID 37685962, 2023). "We applied CCK-8, Edu, Colony formation and Wound healing assays to detect the functions of ULBP2 and TRDV1 in breast cancer cells." (PMID 36092942, 2022). "Then, both univariate and multivariate logistic regression analyses demonstrated that 6 genes regulated by the RUNX family had a significant relationship with the prognosis of breast cancer patients, including PSME2, ULBP2, IL18, TSLP, NPR3, and TRDV1." (PMID 36092942, 2022). "In breast cancer, miR-20a was found to inhibit the expression of MICA/B and ULBP2 by directly targeting MICA/B and downregulating ULBP2 through inhibition of MAPK/ERK, which ultimately resulted in a decrease in the cytotoxicity of NK cells." (PMID 34084160, 2021). "Collectively, these data demonstrate that miR-519a-3p impairs recognition and killing of breast cancer cell by NK cells via direct targeting of MICA and ULBP2 in addition to inhibiting caspase-7-induced apoptosis." (PMID 28771222, 2017). "We assessed the impact of ULBP2 and TRDV1 knockdown on breast cancer cell functions." (PMID 36092942, 2022). "In addition, miR-519a-3p impaired NK-mediated breast cancer cell cytotoxicity by downregulating the expression of MICA and ULBP2." (PMID 32316552, 2020). "Finally, the dual luciferase reporter assay was used to verify the regulation of RUNX3 on potential target genes ULBP2 and TRDV1, and the effects of ULBP2 and TRDV1 on the growth of breast cancer cells were explored by CCK-8, colony formation and wound healing assays." (PMID 36092942, 2022). "High expression of miR-519a-3p in breast cancer was shown to not only induce the expression of TRAIL and FasL to increase the apoptosis resistance of tumor cells, but also reduced the sensitivity of tumor cells to NK cells by downregulating the expression of the NKG2D ligands ULBP2 and MICA." (PMID 34084160, 2021).
cervical cancer (10 papers, 2014 to 2025). A primary or metastatic malignant neoplasm involving the cervix. "Knockdown of ULBP2 inhibits proliferation, metastasis and radiotherapy resistance of cervical cancer cells." (PMID 40640957, 2025). "METTL3 modulates the expression of ULBP2 and affects the physiological function of cervical cancer cells." (PMID 40640957, 2025). "The reduced expression of ULBP2 in cervical cancer suppresses the killing effect of Vδ2T cells on cancer cells, and enhances the proliferation, migration, and invasion of cervical cancer cells." (PMID 36313765, 2022). "ULBP2 increases NK cell cytotoxicity resistance and promotes cervical cancer proliferation, invasion, and migration." (PMID 35060926, 2022). "Intracellular ULBP2 synthesis can be significantly increased by treatment with adrenocorticotropic corticotropin-releasing hormone in HeLa cervical cancer cells and is released from the cells by metalloproteinase to become soluble ULBP2." (PMID 30813924, 2019). "ULBP1 expression was correlated with MICA/B (p < 0.001) and ULBP2 (p = 0.002) expression in cervical cancer." (PMID 25510288, 2014). "More specifically, MICA/B, ULBP1 and RAET1E expression was significantly increased in cervical cancer tissues, while ULBP2 and ULBP3 expression were higher in low-grade CIN tissues, but lower in high-grade CIN and cervical cancer tissues." (PMID 25510288, 2014). "Other studies found that ULBP2 was negatively regulated by miR-873 to inhibit proliferation, invasion, and migration of cervical cancer cells and ULBP2 was bond by miR-6071 to inhibit glioma cell proliferation and invasion and promote cell apoptosis through PI3K/Akt/mTOR pathway." (PMID 36742322, 2023). "A pair of ceRNAs (CA9/ULBP2) could be involved in the carcinogenesis and development of cervical cancer, and the potential target might be hsa-miR-34a." (PMID 36313765, 2022). "Further research found that the ceRNA pairs of ULBP2/CA9 could regulate cervical cancer through hsa-miR-34a." (PMID 36313765, 2022). "In addition, separate analysis of CA9 found that the ceRNA networks (CA9/ULBP2) might regulate the occurrence and development of cervical cancer, but additional experimental results are needed." (PMID 36313765, 2022). "ULBP2 and ULBP3 expression, on the other hand, was higher in low-grade CIN than in normal epithelium but gradually decreased in high-grade CIN and cervical cancer (p = 0.001 and p = 0.017, respectively)." (PMID 25510288, 2014). "We then performed IHC analysis of MICA/MICB, ULBP1, ULBP2, ULBP3, RAET1E, and RAET1G in 200 cervical cancer specimens, 327 high-grade CINs, 99 low-grade CINs, and 541 matched nonadjacent normal cervical epithelial tissue samples." (PMID 25510288, 2014). "Our analysis showed a higher expression of ULBP2 in individuals with cancer, and increased expression of ULPB2 was correlated with poorer survival, indicating that ULBP2 acts as an NK-cell inhibitor in cervical cancer." (PMID 39672307, 2024). "Subsequently, we wanted to know how CA9 works in cervical cancer, then we found that CA9/ULBP2 ceRNA network may be a key mechanism in the pathogenesis of cervical cancer." (PMID 36313765, 2022). "However, metformin did not induce MICB, ULBP1, ULBP2/5/6 and ULPB3 expression on the surface of human cervical cancer cells." (PMID 32631421, 2020).
ovarian carcinoma (10 papers, 2011 to 2025). A malignant neoplasm originating from the surface ovarian epithelium. "The poor prognostic significance of ULBP2 expression in ovarian cancer was confirmed in a second independent study in which MICA/B lacked prognostic significance." (PMID 37626965, 2023). "Specifically, Li and colleagues showed that high expression of ULBP2 detected by immunohistochemistry in 82 ovarian cancer patients correlated with less intraepithelial infiltration of T cells and poor prognosis." (PMID 30150983, 2018). "In ovarian cancer patients, moreover, ULBP2 expression was correlated with poor prognosis." (PMID 36649303, 2023). "Similarly, worsened prognosis of ovarian cancer has been linked to the expression of ULBP1, ULBP3 or RAET1E (ULBP4) in univariate analysis and RAET1E (ULBP4), RAET1G (ULBP5) and ULBP2 in multivariate analysis." (PMID 37626965, 2023). "In contrast to these results, expression of ULBP2 and ULBP4 were found to be independent prognostic factors for a worse outcome of ovarian cancer patients." (PMID 22257486, 2012). "Specific combinations of ligands (e.g. MIC-AB and ULBP-2 in our study, ULBP2 and ULBP4 in ovarian cancer) do show additive effects or statistical interactions on prognostic value." (PMID 22257486, 2012). "Supporting the hypothesis that elevated expression of NKG2D ligands results in immune escape in ovarian cancer, one study found elevated levels of MIC-AB and ULBP-2 to be positively correlated to less intra-tumor epithelial CD57+ cells." (PMID 22257486, 2012).
acute myeloid leukemia (8 papers, 2017 to 2024). Acute myeloid leukemia (AML) is a group of neoplasms arising from precursor cells committed to the myeloid cell-line differentiation. "Sodium valproate, a low affinity pan HDACi, can induce the expression of NKG2D ligands MICA, ULBP2, and ULBP3 in tumor cells, including primary patient acute myeloid leukemia (AML) cells, resulting in enhanced CD107a degranulation of NK cells." (PMID 38665224, 2024). "Shedding of NKG2D ligands, including MICA, MICB and ULBP2, is inhibited by TIMP-3 in acute myeloid leukemia (AML) cells, and this process enhances their sensitivity to lytic activity of NK." (PMID 35207132, 2022). "The LSD1 inhibitor (Tranylcypromine) can upregulate the expression of ULBP2/5/6 by promoting CCAAT/enhancer-binding protein α (C/EBPα) expression in acute myeloid leukemia (AML) cells, thereby increasing NK cells ability to lyse AML cells." (PMID 39629133, 2024).
colon carcinoma (8 papers, 2016 to 2025). "NKCP is significantly associated with colon cancer, and ULBP2 derived from NKCP is a poor prognosis biomarker of colon cancer." (PMID 36742322, 2023). "Thereby, ULBP2 in many malignant tumors, including colon cancer, is a potential clinical diagnostic and therapeutic biomarker." (PMID 36742322, 2023). "In this study, we investigated the effect of ULBP2, a ligand for NKG2D, on the efficacy of CD4+CD25+ T cell-targeted immunotherapies using a CT26 mouse colon cancer model engineered to ectopically express ULBP2." (PMID 40558520, 2025). "This study found that ULBP2 was significantly overexpressed in colon cancer tissues and colon cancer cell lines." (PMID 36742322, 2023). "This study found that a NRG, ULBP2, was highly expressed at the mRNA level in colon cancer tissues and cell line." (PMID 36742322, 2023). "The immunohistochemical analysis revealed that the protein level of ULBP2 was higher in colon cancer tissues compared to adjacent control tissues (p < 0.05)." (PMID 36742322, 2023). "Immunohistochemical analysis also show ULBP2 was highly expressed in colon cancer tissues, which was consistent with previous immunohistochemical report in colon cancer tissues." (PMID 36742322, 2023). "The significantly upregulated ULBP2 was a poor prognostic biomarker of colon cancer." (PMID 36742322, 2023). "To see if the effect of IMP3 on the stress-induced ligands ULBP2 is specific for the colon carcinoma RKO cell line, we performed a knockdown of IMP3 in the colorectal carcinoma HCT116 and in the embryonic kidney-derived cell line 293T and verified the knockdowns using WB." (PMID 26982091, 2016). "When ULBP2 was used alone to distinguish 3-year survival time, the accuracy of logistic regression model was only 59.48%.One study used immune score to predict 3-year prognosis and survival of colon cancer patients, which achieved the AUC values 0.754 in training group and 0.691 in validation group." (PMID 36742322, 2023). "To test this hypothesis, we employed CT26, a murine colon cancer model with high CD8+ T cell infiltration, using mock- or ULBP2-transfected tumor cells to examine the impact of ectopic ULBP2 expression under T cell-modulatory conditions with anti-CD4, anti-CD25, and anti-CTLA-4 antibody treatments." (PMID 40558520, 2025). "qPCR revealed that mRNA level of ULBP2 was higher in colon cancer cells RKO compared to control cells NCM460 (p < 0.05); however, no statistical difference was found in colon cancer cells LoVo compared to control cells NCM460." (PMID 36742322, 2023).
glioma (7 papers, 2014 to 2023). A benign or malignant brain and spinal cord tumor that arises from glial cells (astrocytes, oligodendrocytes, ependymal cells). "Compared to other NKG2DLs, their discovery suggests that the loss of MICA and ULBP2 plays a more significant role in glioma immune escape." (PMID 37565867, 2023). "Additionally, studies on malignant glioma cells revealed that only ULBP2 was shed via ADAM10 and ADAM17 activity." (PMID 33352921, 2020). "Furthermore, IFN-γ decreased transcription of MICA, ULBP1 and ULBP2 in patient-derived melanoma and glioma cell lines in a dose- and time-dependent fashion." (PMID 33352921, 2020). "Similar observations have also been seen with glioma stem-like cells, with ADAM10- and ADAM17-dependent shedding of ULBP2." (PMID 33352921, 2020). "First, we monitored by flow cytometry the cell surface expression of the NKG2D ligand MICA, MICB, ULBP1, ULBP2, ULBP3, ULBP4 and MHC class I on untreated and SR141716-treated U251 glioma cells at 24 h to exclude that the possibility of observed effects are linked to the stress of dying cells." (PMID 26008966, 2015). "Furthermore, although TGF-β signalling increases metalloproteinase expression on glioma cells, the increased shedding of MICA and ULBP2 by glioma cells was not due to TGF-β-dependent metalloproteinases." (PMID 33352921, 2020).
lung carcinoma (7 papers, 2013 to 2025). "In addition to ULBP2, five ligands that we studied were all down-regulated in cisplatin-resistant lung cancer cells." (PMID 28801607, 2017). "Treating NCI-H23 and A549 lung cancer cells with FK228 led to an increase in the transcription of the five NKG2D ligands: MICA, MICB, ULBP1, ULBP2, and ULBP3." (PMID 34203519, 2021). "The transcription of NKG2D ligands, namely, MHC class I polypeptide-related chain proteins A (MICA), MICB, UL16 binding protein 1 (ULBP1), ULBP2, and ULBP3, was analyzed after treating lung cancer cells with five types of HDAC inhibitor for 18 h." (PMID 34203519, 2021). "In our short-term co-culture system, A549 and H1975 lung cancer cells down-regulated surface expression of NKG2D ligands ULBP1, ULBP2 and MICA following co-culture with NK cells." (PMID 23937717, 2013). "The lung cancer cell line A549 highly expressed MICA, MICB, ULBP1, and ULBP2/5/6." (PMID 35965586, 2022). "To investigate whether gefitinib could up-regulate surface ligands for NK cell activating receptors, we co-cultured two human lung cancer cell lines with NK cells and evaluated the expression of ULBP1, ULBP2 and MICA by flowcytometry." (PMID 23937717, 2013).
gastric cancer (6 papers, 2017 to 2025). A primary or metastatic malignant neoplasm involving the stomach. "In fact, MMP-9 associated cleavage and consequent shedding of tumor cell membrane proteins such as MIC-A, MIC-B and ULBP-2, lead to reduced NK associated tumor cell death in gastric cancer, lung adenocarcinoma and osteosarcoma." (PMID 34066355, 2021). "It was also reported that MMP2 in renal carcinoma cells, MMP9 and MMP14 in osteosarcoma cells could increase soluble MICA and MMP9 specific inhibitor could increase MICA/B and ULBP2 in some kinds of gastric cancer cells." (PMID 34253166, 2021).